IL3 (interleukin 3)
Diseases named in the same sentence as IL3 in open-access papers (continued):
Sharing a sentence is not in itself a finding about the gene and the disease.
acute myeloid leukemia (22 papers, 2010 to 2025). Acute myeloid leukemia (AML) is a group of neoplasms arising from precursor cells committed to the myeloid cell-line differentiation. "As a therapeutic aptamer, SS30 effectively inhibits the proliferation of acute myeloid leukemia (AML) cells by blocking the IL-3/CD123 signaling pathway, showing significant anti-tumor potential." (PMID 40422200, 2025). "The TF-1 cells are acute myeloid leukemia cells that depend on GM-CSF or IL-3 for cell survival and proliferation." (PMID 38347540, 2024). "Although data have shown strong correlation between IL-3 and poor survival in acute myeloid leukemia, research on the role of IL-3 in OSCC is scarce." (PMID 32961854, 2020). "The top down-regulated canonical pathways in which under-represented proteins were detected were putative molecular mechanisms of cancer, acute myeloid leukemia signaling, erythropoietin signaling, mechanisms of viral exit from host cells and IL-3 signaling." (PMID 26538867, 2015). "A recent study identified an activating allele of JAK3 (V674A) from an acute myeloid leukemia patient-derived retroviral cDNA library, and showed that JAK3V674A can transform the lymphoid pro-B-cell line BaF3 to IL-3-independent growth." (PMID 20149240, 2010). "Since then, a series of differentiation regulators, including retinoic acids, granulocyte-macrophage colony-stimulating factor, and interleukin-3, have been used in several tumor types such as osteosarcoma, acute myeloid leukemia (AML), pancreatic cancer, liver cancer, and NB (de Thé, 2018)." (PMID 37745860, 2023). "When comparing newly diagnosed patients with acute myeloid leukemia (AML) and acute lymphoblastic leukemia (ALL), AML showed a significant increase in IL-4, IL-2 and IL-3, and a significant decrease in VEGF and VCAM-1." (PMID 40427092, 2025). "In vitro and murine studies demonstrated that constitutively active Flt3 mutants allow acute myeloid leukemia cells to grow in the absence of interleukin 3 (IL-3)." (PMID 33363015, 2020). "The hematopoietic GTPase RhoH acts as a negative regulator for IL-3-induced signals by controlling STAT activity and IL-3 Receptor α expression, ultimately resulting in the preferential activation of STAT1 and decreased cell proliferation in acute myeloid leukemia." (PMID 38702781, 2024). "In tumor cells, dysregulated expression of IL-3 is the molecular basis for survival and proliferation leading to malignancies, including mast cell leukemia (MCL), acute myeloid leukemia (AML), and chronic myeloid leukemia (CML)." (PMID 25749030, 2015).
Allergy (19 papers, 2012 to 2025). An allergy is an immune response or reaction to substances that are usually not harmful. "The IL-13 gene is located on the 5q31 chromosome, which also encodes other factors involved in allergy mechanisms such as IgE, IL-4, IL-3, and IL-5." (PMID 35629280, 2022). "Other studies suggest the possible involvement of the Th2 pathway in non-IgE-mediated allergies, with findings of elevated serum levels of cytokines such as IL-3, IL-5, and IL-13 in patients with this type of allergy." (PMID 41394805, 2025). "TMPRSS2 reduces the recognition of viruses through human defense mechanisms; however, type 2 inflammation, in which interleukin (IL)-4, IL-5, and IL-3 are important inflammatory factors, acts as the inflammatory basis of allergic diseases in children." (PMID 38646512, 2024). "Numerous studies support IL-3-dependent basophil activation and cytokine release in murine allergy models, highlighting the contribution of IL-3 in allergic asthma." (PMID 37275910, 2023). "In contrast, we noted a significant increase in tryptase (mean increase = 1.34 ng/mL) and IL-3 (mean increase = 1.09 pg/mL) results compared with baseline in participants during clinical allergic reactions." (PMID 37402149, 2023). "Alleviation of allergy symptoms is due mostly to the manipulation of proinflammatory cytokines secreted by mast cells, and IL-3, IL-4, and IL-13 are regarded as critical therapeutic targets in allergic inflammatory illnesses." (PMID 36142314, 2022). "Eosinophils are also present in healthy individuals, but in allergic diseases the release of various mediators such as IL-5, IL-3, and GM-CSF promotes the production and activation of the cells." (PMID 32280308, 2020). "In contrast, Th2 cells mainly secrete IL-4, IL-3, IL-6, and IL-10 to stimulate the proliferation of activated B cells, to produce antibodies, and to participate in humoral immune-related or allergic diseases." (PMID 33659270, 2020). "In the late phase allergic reaction, Th2 cells and mast cell-derived cytokines namely IL-3, IL-5 and GM-CSF are involved in the eosinophil activation and recruitment of leukocytes to the region of allergen exposure." (PMID 31694050, 2019). "In summary, our data indicate that the IL-3-induced subthreshold IKK activation is an important mechanism that mediates pathological effector functions in inflamed tissues after infection, allergy, necrosis and supports survival of tumor cells." (PMID 25749030, 2015). "Last, IL-3 is upregulated during infection, autoimmune disease, allergies, and AML, and the chronic inflammatory conditions in germline RUNX1 disease may elevate basal IL-3 levels." (PMID 37581927, 2023). "Our data provide novel insights about IL-3 as an inducer of M-MDSC, which paves the way for further molecular investigations on their signaling, but also about their role in vivo in type 2 diseases such as allergies and helminth infections." (PMID 37275910, 2023). "Therefore, the synergistic interaction between IL-3 and certain alarmins on the release of immunomodulatory cytokines from hBaso and mBaso might be relevant in the pathophysiology of different basophil-mediated disorders such as allergic diseases, parasitic infections, autoimmunity, and cancer." (PMID 35693823, 2022). "In addition, animal studies have demonstrated that lactic acid bacteria can induce the production of IL-12 and IFN-γ, reduce the production of IL -4, IL-5 and IL-3, promote the immune response of TH1 and inhibit the occurrence of allergic reactions." (PMID 32358397, 2020).
myeloma (17 papers, 2012 to 2023). "Malignant myeloma cells secrete several cytokines, such as tumor necrosis factor, interleukin-3, receptor activation of NFκB ligand, and macrophage inflammatory protein-1α, which increase osteoclaster-mediated bone destruction." (PMID 37109052, 2023). "Osteoclasts have been found to influence myeloma progression via direct crosstalk or release of distinct cytokines including IL-6, IL-3, macrophage inflammatory protein 1 alpha (MIP1α) or expression of receptor activator of NF-κB ligand (RANKL)." (PMID 35847862, 2022). "Expression of RANKL and secretion of IL-6, MIP1α or IL-3 by myeloma cells activates osteoclasts and thereby increases resorption of bone matrix." (PMID 35847862, 2022). "The interaction between plasma cell myeloma cells and pDCs stimulate IL-3 expression, which consequently enhances myeloma cells’ development and increases pDC survival." (PMID 33113953, 2020). "Multiple myeloma cells have been shown to produce factors that inhibit osteoblast differentiation and growth, including IL-3, TNF-alpha, and TGF-beta." (PMID 29867053, 2018). "Furthermore, induction of IL-3 expression in the bone marrow microenvironment of patients with myeloma has been shown to increase bone destruction and promote tumor cell growth." (PMID 35479514, 2022). "Some investigators have concluded that the leukocytosis is in response to the myeloma because monoclonal B-cell clones in myeloma can produce cytokines which are able to activate stromal cells to produce IL-6, IL-7, and IL-11 to stimulate T lymphocytes to produce IL-3 and GM-CSF." (PMID 25143840, 2014). "Furthermore, IL-3 can significantly upregulate the high-affinity receptor, IL-6, in myeloma cells." (PMID 37250588, 2023). "Some cytokines such as IL-7, IL-3, IL-6, TNF-α produced by myeloma cells can inhibit the differentiation and activativity of osteoblasts and induce osteoblasts apoptosis." (PMID 25788856, 2014). "In addition, IL-3 and IL-5 share a common signal transduction chain, KH97, with CSF2, which can increase the sensitivity of myeloma cells to these cytokines." (PMID 37250588, 2023).
melanoma (15 papers, 2013 to 2024). A malignant, usually aggressive tumor composed of atypical, neoplastic melanocytes. "Our data demonstrated that proliferating moTAMs generated with IL-3 in combination with M-CSF resemble the CD163+ TAMs found in the melanoma TME." (PMID 38903497, 2024). "The deletion of the BH4 region in a human fibroblast cell line largely impairs cell viability under IL-3 deprivation and melanoma growth in vitro and in vivo." (PMID 38062391, 2023). "In melanoma bearing mice IL-3 has been reported to bias the hematopoietic development towards a dysregulated state with increasing MDSC frequencies." (PMID 37275910, 2023). "Using melanoma conditioned media, the authors show IL-3 drives an expansion of lin-, LSKs, myeloid precursors, CMPs, and GMPs from whole BM cells." (PMID 33919157, 2021). "One of the earliest observations in melanoma was that of mast cell recruitment to the perilesional stroma by chemotactic factors, such as IL-3, produced by melanoma cells." (PMID 31861163, 2019). "It has previously been reported that IL-3 is expressed in the vast majority of primary melanomas." (PMID 38903497, 2024). "IL-3 is a pro-tumoural cytokine reportedly present in more than 80% of primary malignant melanoma." (PMID 38903497, 2024). "IL-3 has been reported to skew the in vitro generation of macrophages towards an M2 effector phenotype by supportive signals from IL-4 or IL-13 produced by basophils, but also to promote immunosuppressive myeloid cells in a murine melanoma model." (PMID 37275910, 2023). "Thus, expanding these cells with IL-3/anti-IL-3 therapy increases the CD8 T-cell recruitment in melanoma tumors and delays the tumor growth in a CCL3/CCL4-dependent manner." (PMID 36429101, 2022). "A study on melanoma brain metastases found that astrocytes can produce interleukin (IL)-3, CD40L, CXCL 12, interferon-γ, and other cytokines that stimulate melanoma cells; in this context, IL-23 stimulates tumor cells to produce MMP-2, thereby promoting tumor cell proliferation." (PMID 36338717, 2022). "Finally, the authors administered anti-IL-3 to melanoma-bearing mice and analyzed the spleen immune cell populations, and found increased frequencies of lineage-, LSKs, and myeloid precursors relative to mice treated with isotype control." (PMID 33919157, 2021). "Loratadine was predicted to interact with interleukin 3 (IL3; hsa:3562) based on its transcriptional similarity (score = 0.838) with amlexanox (D01828), where both gene expression signatures were obtained from the A375 cell line derived from a melanoma." (PMID 28071740, 2017). "The IL-3 growth factor is able to upregulate CCR6 expression on human blood pDCs; however, it is so far undetermined whether IL-3 or other factors produced by cells of the TME are responsible for CCR6 upregulation by melanoma-associated pDCs." (PMID 39020402, 2024). "Furthermore, the IL-3/anti-IL-3 antibody complexes combined with adoptive T cell transfer induced basophilia and consequent T cell infiltration, which positively correlated with melanoma rejection." (PMID 36578500, 2022). "Therefore, taken together, reduced levels of RANTES, IL-3 and IL-10 may be involved in the anti-melanoma immune response under NAM treatment." (PMID 33028392, 2020). "Compared to other monocyte-derived cell types including moDCs and moMACs, moTAMs generated with IL-3 and M-CSF were superior in modulating the proliferation of allogeneic T cells and CD8+ T cells specific for an immunodominant melanoma antigen." (PMID 38903497, 2024). "In the antigen presenting cells, (APC)/Cytokine/Chemokine/Immune category, differences in IL-2, IL-3 and STAT3 signaling pathways in melanoma and Wnt, Rho GTPases MAPK4/6 signaling pathways in HD mDC were observed." (PMID 37938561, 2023).
melanoma (continued). "Most secreted factors (TNFα, GM-CSF, G-CSF, PDGF-BB, CCL5, CCL11, IL-3, IL-6) were not induced by exogenous IFNγ in our panel of melanoma cells, confirming the complex inflammatory signaling profile of de-differentiated PD1 PROGs with intrinsic IFNγ signaling." (PMID 36934113, 2023).
chronic myeloid leukemia (14 papers, 2012 to 2025). "IL-3 over-expression in chronic myelogenous leukemia (CML) patients has also been associated with imatinib resistance." (PMID 24658545, 2014). "The highly expressed interleukin-3 (IL3) receptors in chronic myeloid leukemia (CML) cells can serve as drug targets." (PMID 40804047, 2025). "For example, interleukin-3 (IL-3) expressed on the surface of EVs can be used to target the delivery of EVs to the IL-3 receptor that is highly expressed in chronic myelogenous leukemia cells compared with that in normal hematopoietic cells." (PMID 38660297, 2024). "Another study engineered sEVs derived from HEK293T cells with a fragment of IL-3 to target overexpressed IL-3 receptor (IL-3R) in chronic myeloid leukaemia (CML) cells." (PMID 36167539, 2022). "These sEVs produced by modified HEK293T cells combined with interleukin-3 (IL3) fragments were able to target IL3 receptor-rich chronic myeloid leukemia mother cells and inhibit their growth." (PMID 34094979, 2021). "The interleukin-3 (IL-3) receptor is a cell-surface heterodimer that links the haemopoietic, vascular and immune systems and is overexpressed in acute and chronic myeloid leukaemia progenitor cells." (PMID 29374162, 2018). "For instance, Lamp2b-IL-3 expressing exosome was developed to target chronic myeloid leukemia (CML) cells preferentially as they overexpress IL-3 receptors." (PMID 30061829, 2018). "For example, exosomes with Lamp2b-IL-3 have been used to target chronic myeloid leukemia (CML)." (PMID 36258195, 2022).
schizophrenia (13 papers, 2009 to 2025). A major psychotic disorder characterized by abnormalities in the perception or expression of reality. "Genetic studies have shown that the IL-3 and IL-3 receptor alpha subunit (IL-3RA) genes are located near genetic markers associated with schizophrenia." (PMID 33746786, 2021). "The reported association studies on SCZ patients is consistent with our observation, in which IL3 showed a significant association with schizophrenia only in females." (PMID 23226269, 2012). "Genetic variants in the 5q region have previously been found to be associated with schizophrenia (e.g., IL3, IL4, IL9, NEUROG1)." (PMID 22723893, 2012). "It was found to interact with the interleukin 3 (IL3) gene and jointly contribute to schizophrenia risk." (PMID 19128481, 2009). "A significantly positive association between the Positive and Negative Syndrome Scale (PANSS) general psychopathology subscore and IL-3 was also described in chronic medicated patients with schizophrenia." (PMID 33746786, 2021). "On chromosome 5q, several schizophrenia-related SNPs and haplotypes both in and near the IL-3 cytokine gene have been identified." (PMID 33746786, 2021). "In previous research, for instance, it has been observed that the serum levels of cytokine IL-3 are significantly elevated in patients with long-term schizophrenia." (PMID 29757197, 2018). "Interestingly, we noticed that rs3916441, which is most significantly associated with brain volume, was also significantly associated with schizophrenia in females, implying the interaction between IL3 and gender may play vital roles in normal brain development and schizophrenia susceptibility." (PMID 23226269, 2012). "Also, our findings support a previous study that found a positive correlation between high IL-3 levels and depressive symptoms in schizophrenia." (PMID 37957650, 2023). "These convergent evidences strongly indicate the involvement of the IL3 pathway in schizophrenia." (PMID 23226269, 2012). "In addition, decreased IL-3 levels in the first-episode and drug-naïve patients with schizophrenia was also reported." (PMID 23226269, 2012). "Collectively, these results provide novel insights to the involvement of IL3 in brain development, supporting the neurodevelopmental hypothesis of schizophrenia." (PMID 23226269, 2012). "For example, several interleukin genes (IL2, IL3, IL4) have been implicated for schizophrenia." (PMID 20613869, 2010). "Collectively, these studies support a role for the IL3/CSF2 pathway in schizophrenia." (PMID 19721717, 2009). "As a consequence, it has been speculated that reduced IL-3 levels in FEDN patients might be associated with both neuronal apoptosis and abnormal early development of the CNS, which may potentially be implicated in the pathogenesis of schizophrenia." (PMID 33746786, 2021).
viral infections (13 papers, 2013 to 2025). "Previously, we showed that IL-3 protects against primary viral infection by promoting the recruitment of pDCs into the lungs in a CXCL12-dependent manner." (PMID 36911737, 2023). "Bcl-xL cleavage has also been reported to result from different stimuli such as IL-3 withdrawal, virus infection, caspase-3-like proteases from an apoptotic CTLL-2 cell lysate, or the direct activation of caspase-9 by chemically induced dimerization." (PMID 33076337, 2020). "Using mouse models of bacterial and viral infections, we showed that IL-3–secreting CD4+ T cells were generated by infection at the skin and mucosa but not by infections introduced directly into the blood." (PMID 31356170, 2019). "Cytokines and chemokines that showed limited response in mice with any viral infection included Eotaxin, GM-CSF, IL-1α, M-CSF, IL-2, IL-3, IL-4, IL-5, IL-7, IL-9, IL-12p40, IL-13, IL-15, IL-17, MIP2, LIX, MIP1β, RANTES, IL-12p70, and VEGF (data not shown)." (PMID 23441208, 2013). "Collectively, our results revealed a new function of IL-3 during viral infection and confirmed that IL-3 may be a potential therapeutic target to control primary and secondary viral pneumonia." (PMID 36911737, 2023). "RT-qPCR analyses confirmed the higher expression of genes associated with inflammation in the lungs of infected CLP Il-3-/- mice compared to CLP WT mice, suggesting that the inability to control the viral infection observed in CLP Il-3-/- mice may result in increased lung tissue damage." (PMID 36911737, 2023). "However, the impact of IL-3 in the subsequent immunosuppressive phase, in which secondary viral infections and viral re-activations occur, remains unclear." (PMID 36911737, 2023). "However, the effect of IL-3 on pDCs during viral infection is still poorly understood." (PMID 36911737, 2023). "In addition, since the type I and type III interferons are largely derived from pDCs during viral infections, their production in hβcTg mice suggests that IL-3 may have a limited role in pDC expansion during influenza infection." (PMID 35145069, 2022). "This study identifies IL-3 as a predictive disease marker for SARS-CoV-2 infections and as a potential therapeutic target for pulmunory viral infections." (PMID 33602937, 2021). "Second, we determined that IL-3 promotes the recruitment of pDCs into the lungs of CLP mice during viral pneumonia and that the ex vivo stimulation of human circulating pDCs by IL-3 results in increased T cell activation upon viral infection." (PMID 36911737, 2023).